IL6 (interleukin 6)
Diseases named in the same sentence as IL6 in open-access papers (continued):
Sharing a sentence is not in itself a finding about the gene and the disease.
Insulin resistance (continued). "Here, we measured the levels of inflammatory cytokines in rats by qPCR, including TNF-α, IL-1β, and IL-6, which are key proinflammatory factors in type 2 diabetes and closely related to insulin resistance." (PMID 37072819, 2023). "Novel approaches indicate that insulin resistance is produced in RA patients due to the increase in energy expenditure via high levels of IL-6 in the serum." (PMID 38069224, 2023). "For example, NK cells can produce pro-inflammatory cytokines (e.g., IFN-γ, TNF-α, IL-1, IL-6, and IL-12), which can exacerbate hepatic inflammation and promote insulin resistance." (PMID 37361209, 2023). "It is known that in insulin resistance, there is an increase in pro-inflammatory cytokines such as interleukin (IL)-1, IL-6, and tumor necrosis factor (TNF)-α." (PMID 37629193, 2023). "Omega-3 supplementation of 900 mg/day in 87 postmenopausal women significantly reduced BMI, waist circumference, TG levels, and interleukin-6 concentrations and improved insulin resistance." (PMID 37432253, 2023). "Proinflammatory mediators such as TNF-α, IL-6, and IL-1β played pivotal roles in the development of insulin resistance in adipose tissue of HFD-fed obese mice." (PMID 37111032, 2023). "Then the macrophages and adipocytes secrete TNF-α, IL-6, and other inflammatory factors, which lead to insulin resistance, insulin secretion dysfunction, and metabolic syndrome." (PMID 37072819, 2023). "Adipose tissue produces a large number of pro-inflammatory cytokines, such as TNF-α, monocyte chemotactic protein-1 (MCP-1), IL-6, and C-reactive protein, which promote chronic inflammation, decreased muscle protein synthesis, and insulin resistance." (PMID 37424859, 2023). "Pro-inflammatory cytokines including IL-6 are often elevated in obese people, and this increase is correlated with the development of insulin resistance and predictive of fully-established T2D." (PMID 36672202, 2023). "The involvement of IL-6 signaling in insulin resistance has sparked controversy, displaying occasional paradoxical effects." (PMID 38004353, 2023). "Interleukin-1 (IL-1), interleukin-6 (IL-6), and tumor necrosis factor-α (TNF-α) are inflammatory cytokines that cause insulin resistance and also suppress insulin release, an effect that is concentration-dependent." (PMID 35959169, 2022). "Interleukin-6 (IL-6) stimulates the secretion of hepatic TGs and plays a role in insulin resistance (IR) at the cellular level in hepatocytes." (PMID 36470993, 2022). "Increased secretion of IL6 from the adipose tissue induces “chronic low-grade inflammation” and insulin resistance." (PMID 36452038, 2022). "We presumed that IL-6 and TNF-α were associated with a pro-inflammatory state leading to insulin resistance and diabetes." (PMID 36140983, 2022). "The activation promotes the expression of target genes IL-6 and TNF-α to cause low-grade systemic inflammation and insulin resistance." (PMID 36235858, 2022). "The systemic levels of TNF-α and IL-6 are elevated in DM, and can directly promote insulin resistance." (PMID 35805932, 2022). "Increased plasma levels of inflammatory mediators, e.g., C-reactive protein, leukocytes or interleukin 6 (IL-6), have been shown to predict the development of insulin resistance and type 2 diabetes." (PMID 35885586, 2022). "This suggests that there is a relationship between acanthosis nigricans, a sign of insulin resistance, adiposity, and the increase in IL-6." (PMID 36140983, 2022). "This provides a better understanding of the genetic susceptibility and pathogenesis of NASH, with the IL6-174C polymorphism being an independent predictor of both NAFLD and NASH, and also involved in inflammation and insulin resistance." (PMID 36035124, 2022). "They trigger NF-κB and AP-1, produce IL-6 and TNF-α that affect insulin sensitivity by altering the expression of genes encoding IRS-1, GLUT-4, and PPAR-α and lead to insulin resistance." (PMID 36140983, 2022).
Insulin resistance (continued). "Increased IL-6 release from adipose tissue contributes to the development of insulin resistance either by reducing adiponectin secretion, as demonstrated by our findings, or by influencing the insulin signal transduction pathway in hepatocytes." (PMID 36364860, 2022). "Factors that contribute to pregnancy-induced insulin resistance include the secretion of adipokines (e.g., leptin) and cytokines (e.g., tumor necrosis factor-alpha, interleukin-6, and interleukin-1β), oxidative stress and, possibly, the gut microbiome." (PMID 33536549, 2022). "Evidences indicate that insulin resistance can impact the increase of IL-6, and in TLRs, more specifically, type 4 (TLR-4), these mechanisms aremediated by the STAT3 pathway in skeletal muscle." (PMID 35052633, 2022). "Patients with severe CAP have inflammatory immune activation (manifested by an increased IL-6 level and IL-16/IL-10 ratio), acquired growth hormone (GH) resistance, and insulin resistance." (PMID 35619955, 2022). "YP-SJ formula can significantly improve insulin resistance and reduce the level of IL-6, a vascular inflammatory factor, in type 2 diabetic patients." (PMID 36147338, 2022). "Other pro-inflammatory cytokines can contribute to the development of MAFLD and colorectal tumors by inducing metabolic liver inflammation and insulin resistance through various complex inflammatory signaling pathways, such as IL-6 and TNFα." (PMID 35668493, 2022). "Mast cells were positively corelated with components of MetS, such as WC, raised TG and insulin resistance, as well as inflammatory markers such as IL-1β and IL-6, suggestive of an inflammatory role in pathogenesis of MetS." (PMID 36103469, 2022). "For example, IL-6 directly inhibits insulin sensitivity and upregulates the release of hormones that contribute to insulin resistance via induction by insulin receptor's signal transduction in hepatocytes." (PMID 35647197, 2022). "FFA activated TLR 4/TLR 2, stimulated nuclear factor kappa B (NF-κB) and Jun amino-terminal kinase (JNK) signaling, induced the expression of inflammatory cytokine genes, such as TNF-α and IL-6, and aggravated insulin resistance in adipocytes and macrophages." (PMID 35432210, 2022). "Among several inflammatory biomarkers, Il-6 has been shown to predict the development of type 2 diabetes, promoting the development of inflammation, insulin resistance, and β-cell dysfunction." (PMID 35323474, 2022). "Interleukin-6 (IL-6), together with monocytochemotactic protein-1 (MCP-1), is a pro-inflammatory cytokine associated with the development of insulin resistance and hyperglycaemia." (PMID 36013366, 2022). "Eventually, when increasing, it leads to an increase in inflammatory factors such as TNF-ɑ and IL-6, resulting in insulin resistance in the body." (PMID 36159326, 2022). "The acetic acid concentration was weakly negatively correlated with blood glucose indicators and insulin resistance, and negatively correlated with serum IL-6, TNF-α, and IFN-γ concentrations." (PMID 35745208, 2022). "Several studies have investigated the relationship between STAT3 activation and insulin resistance, indicating mediation between specific tissues (hepatic and muscle), cytokines (IL-6), and adipokines (visfatin), in addition to the signpost SOSC3/STAT3." (PMID 35052633, 2022). "It reduces the action of adipocytokines such as leptin, TNF-α, and IL-6, as well as oxidative stress, which leads to an improvement of insulin resistance." (PMID 35742443, 2022). "IL-6 is a major pro-inflammatory cytokine in chronic inflammation that is closely related to insulin resistance, neurodegeneration, cardiovascular disease (CVD), and malignancy." (PMID 35433780, 2022). "A polymorphism in the gene encoding for apolipoprotein C3 and IL-6 polymorphisms were associated with NAFLD, inflammation and insulin resistance." (PMID 36555867, 2022).
Insulin resistance (continued). "Fourth, circulating IL-6 also stimulates the hypothalamic-pituitary-adrenal (HPA) axis, the activation of which is associated with central obesity, hypertension, and insulin resistance." (PMID 35887619, 2022). "It is noteworthy that the P13K-AKT pathway affects a variety of downstream effector molecules such as IL-6, NF-κB and IL-1β, which play an important role in the occurrence and development of diabetes through inflammatory immune response and insulin resistance." (PMID 36559019, 2022). "IL-6-activated STAT3 can induce insulin resistance through suppressors of cytokine signaling 3 (SOCS3); it can then inhibit the PI3K-AKT pathway, which reduces protein synthesis and increases myostatin transcription." (PMID 35846289, 2022). "Both TNF-α and IL-6 can lead to insulin resistance by triggering different key steps in the insulin signalling pathway." (PMID 36501129, 2022). "Increased inflammatory cytokines like TNF-α and IL-6 secreted by visceral adipocytes along with cytokines specific for adipocytes are the key players in inducing insulin resistance." (PMID 37654824, 2022). "Previous studies suggest that IL-6 is a proinflammatory cytokine that plays an important role in white adipose tissue dysfunction and hepatic insulin resistance, which was consistent with our results." (PMID 35894174, 2022). "High serum levels of IL-6, IL-8 and VEGF have been associated with poor BC prognosis/overall survival, but also with insulin resistance and diabetic complications." (PMID 36358839, 2022). "This has consequences for the foetus with increased leptin and IL-6 in umbilical cord plasma and acquisition of insulin resistance in utero of new borns of obese mothers." (PMID 35348641, 2022). "Studies have shown that inflammation is associated with insulin resistance, and the most vital pro-inflammatory mediators include tumor necrosis factor-α (TNF-α) and interleukin 6 (IL-6)." (PMID 36232291, 2022). "We discovered that the new nutraceutical was able to improve insulin resistance and hepatic steatosis mainly by regulating IL-6, IL-10, and Pgc-1α gene expression." (PMID 35326098, 2022). "Macrophages present a constitutive expression of JAK/STAT-activating cytokine Unpaired 3 (Upd3) in Drosophila or interleukin-6 (IL-6) in humans, which have been considered as the critical factor inducing insulin resistance." (PMID 37073169, 2022). "First, anti-inflammatory naringin can effectively diminish the secretion of diabetes-associated inflammatory molecules, such as interleukin-6 (IL-6) and TNF-α, both of which contribute to insulin resistance and hyperglycemia." (PMID 35529431, 2022). "Low IGF-II levels have been reported in obese children, especially in those with insulin resistance and increased inflammatory markers, such as IL-6 and TNF-a." (PMID 36292046, 2022). "The mRNA expressions of TNF-α, IL-6, and angiopoietin-like 4 (Angptl4), which are involved in insulin resistance, were shown to be higher in the adipose tissue of mice from the P. gingivalis-administered group." (PMID 36299624, 2022). "The concentrations of propionic acid and butyric acid were negatively correlated with blood glucose indicators and insulin resistance, and negatively correlated with serum IL-6 and TNF-α concentrations." (PMID 35745208, 2022). "This can be due to the enhanced viral-induced inflammation, in particular, interleukin 6 (IL-6) mediated, which increases insulin resistance in a dose-dependent manner." (PMID 36619546, 2022). "IL6 was verified to implicate in the pathogenesis of CHD, possibly due to its association with inflammation, insulin resistance, and plasma ceramides." (PMID 35783840, 2022). "TNF-α and IL-6, as proinflammatory factors, from obese adipose tissue contribute to insulin resistance by impairing insulin receptor activation, upregulating insulin and insulin-like growth factor-1 (IGF-1) levels." (PMID 35964108, 2022).
Insulin resistance (continued). "IL-6 affects chronic inflammation, fat metabolism, and insulin resistance, and the expression of IL-6 induces other inflammatory cytokines such as TNF-a and IL-1." (PMID 36616208, 2022). "It is noteworthy that IL-6 has been considered a mediator between inflammatory processes derived from insulin resistance conditions." (PMID 35052633, 2022). "P. gingivalis infection increased systemic inflammation, especially in adipose tissue, through the induction of IL-6, which can induce insulin resistance." (PMID 36299624, 2022). "Cohort studies of a Caucasian population demonstrated that the prevalence of IL6-174C variant was higher in NASH than NAFLD patients, and was associated with increased insulin resistance." (PMID 36035124, 2022). "Even when fed an HFD, Il-6-/- mice showed a significantly worse fatty liver disease phenotype and insulin resistance compared with control animals." (PMID 36013467, 2022). "Prolonged IL-6 stimulation enhanced glucose uptake, but induced insulin resistance by inhibiting expression of IRS-1, in cultured murine 3T3-L1 adipocytes." (PMID 35557517, 2022). "High levels of proinflammatory cytokines in diabetes, such as IL-6 and TNF-α, cause disruption of the inflammatory, hyperinflammatory cascade, and insulin resistance." (PMID 35186344, 2022). "Adipose tissue can secrete proinflammatory cytokines such as interleukin 6 (IL-6) and tumor necrosis factor alpha (TNFα), which contribute to insulin resistance (IR)." (PMID 35586621, 2022). "IL-6 is one of the cytokines released by both macrophages and adipocytes, and its levels were shown to be increased with insulin resistance and obesity." (PMID 35054972, 2022). "The BSME-treated, maturing, adipocyte-secreted proteins were detected with a decreased protein level of leptin, TNF-α, IL-6 and STAT-6, which are associated with insulin resistance and macrophage recruitment." (PMID 35209178, 2022). "Insulin resistance seems to promote the development of Th1 inflammation through the production of pro-inflammatory molecules (i.e., IL-6, TNF-α)." (PMID 35055456, 2022). "Treatment with AD-MSCs and AD-MSCs preconditioned with OXA were reported to decrease TNF-α and IL-6 levels significantly as compared to group II which can improve insulin resistance (p < 0.001)." (PMID 35083338, 2022). "The role of interleukin-6 (IL-6) concerning the severity of hepatocyte inflammation, staging of fibrosis and insulin resistance in NASH and NAFLD, has been reviewed in the literature by various authors 2324." (PMID 35204498, 2022). "Following adipocyte death, macrophages M1 (stimulators of pro-inflammatory factors and inducers of insulin resistance) produce inflammatory cytokines such as IL-6, TNF-α, IL-1β, and monocyte chemoattractant protein (MCP-1)." (PMID 35055456, 2022). "Third, as well as being an energy-storing organ, adipose tissue is the largest endocrine organ producing adiponectin, leptin, TNF-α, and IL-6, which leads to systemic inflammation and insulin resistance, thereby further exacerbating NAFLD." (PMID 35453642, 2022). "Our observation is concomitant to previous studies where IL6 and TNFα were found to be elevated in patients with lipid abnormalities and insulin resistance." (PMID 35360165, 2022). "TLR4 signaling leads to the activation of the NFκB pathway, which results in the secretion of inflammatory mediators (e.g., TNFα, MCP-1, and IL-6) and stimulates insulin resistance." (PMID 35889783, 2022). "Improvement in insulin resistance has been reported to be related to chronic inflammation which can be measured by c-reactive protein, interleukin-6, or TNF-alpha or oxidative stress." (PMID 35242882, 2022). "The mechanism of IL-6-induced insulin resistance in the liver involves the activation of STAT3 and subsequent induction of the SOCS3 suppressor." (PMID 35052633, 2022).
Insulin resistance (continued). "Two commonly measured cytokines, IL-6 and TNF-α, have been associated with insulin resistance, diabetes, and obesity, cardiac disease, and cancer in humans." (PMID 36230446, 2022). "Peripheral administration of IL-6 in mice induces insulin resistance, and peripheral IL-6 antibody neutralisation of IL-6 in a transgenic diabetes mouse model improves hepatic insulin sensitivity." (PMID 35470093, 2022). "Inflammatory cytokines such as interleukin (IL)-6 have been found to be involved in the pathogenesis of both insulin resistance and atherosclerosis." (PMID 36232386, 2022). "Their activation is dependent on the same IKK-β implicated in the pathophysiology of insulin resistance, and results in PPAR-γ mediated secretion of IL-1β, TNF-α, IL-6, IL-12, and IL-23." (PMID 36615781, 2022). "In T2DM, as well as in insulin resistance, there is increased production of IL-6, IL-1β, IL-18, tumor necrosis factor (TNF-a), alpha-1 antichymotrypsin and C-reactive protein." (PMID 35453527, 2022). "In fact, IL-6 is known to regulate fat and glucose metabolism, mediating insulin resistance by way of different complex mechanisms." (PMID 35054972, 2022). "High levels of proinflammatory cytokines such as IL-6 and TNF-α in diabetes cause disruption of the inflammatory cascade, hyper inflammation, and insulin resistance." (PMID 35186344, 2022). "As one of the main pro-inflammatory cytokines, IL-6 is involved to a high degree in the activity of systemic inflammation and thus in the development of insulin resistance and DM." (PMID 36422195, 2022). "Insulin resistance is also associated with the increased level of pro-inflammatory cytokines—TNF alfa, IL-6." (PMID 35054072, 2022). "Among 25 participants with insulin resistance and metabolic syndrome, fenofibrate reduced plasma TG as well as inflammatory markers interleukin-6 (IL-6) and high-sensitivity C-reactive protein (hsCRP), but did not improve insulin sensitivity." (PMID 35457120, 2022). "IL-6 is a pleiotropic and multifaceted cytokine that is involved in the induction of insulin resistance and pathogenesis of T2D, and secretion of IL-6 by AT resulted in the induction of hepatic insulin resistance." (PMID 35625566, 2022). "First, insulin resistance is common in CKD, possibly related to pro-inflammatory cytokines such as interleukin-6 and tumor necrosis factor-⍺ and oxidative stress that are involved in intracellular mechanisms of insulin resistance." (PMID 35189851, 2022). "But in an obese state, Ly6chigh monocytes infiltrate tissues and differentiate into M1 type macrophages, which produce inflammatory cytokines, such as TNF-α, IL-6, IL-1β, and IL-18, and drive insulin resistance." (PMID 36015301, 2022). "• Prevalence of IL6-174C variant was higher in NASH than NAFLD patients in a Caucasian population and was associated with increased insulin resistance." (PMID 36035124, 2022). "Moreover, enhanced inflammation in liver and skeletal muscles and insulin resistance was observed in hepatocyte-specific IL-6R deficient animals, as well as increased insulin resistance in whole-body IL-6 KO mice and increased body weight in astrocyte-specific IL-6 deficient mice." (PMID 36387898, 2022). "Hypertrophic adipocytes produce abnormal adipokines and cytokines, such as TNF-alpha, MCP-1, FFA, IL-6, and resistin, which inhibit insulin signaling in hepatocytes and induce insulin resistance." (PMID 36615686, 2022). "Muscle fibers produce cytokines and other peptides such as interleukin-6, which affect the immune response by inhibiting the production of tumor necrosis factor-α and insulin resistance." (PMID 36684364, 2022). "Research has shown that W. coagulans can inhibit the HFD-induced expression of inflammatory cytokines IL-1β and IL-6 in the liver to improve systemic inflammation and insulin resistance." (PMID 36235858, 2022).